STYXL2 (serine/threonine/tyrosine interacting like 2)
Description:
May be required for myofiber maturation.
Synonyms: DUSP27
Tractability: No criterion of Open Targets' tractability assessment is met for any kind of drug.
Gene: Protein-coding gene on chromosome 1 (167,094,075 to 167,129,165, forward strand). Ensembl gene ENSG00000198842.
Subcellular location: Cytoplasm, myofibril, sarcomere
Subcellular location (Human Protein Atlas): Nucleoplasm
Gene Ontology:
Molecular function: MAP kinase phosphatase activity; protein tyrosine/serine/threonine phosphatase activity; phosphatase activity
Biological process: negative regulation of MAPK cascade
Cellular component: cytoplasm; sarcomere
Genetic constraint (gnomAD): Loss-of-function variants: 44 observed, 53.19 expected, observed/expected ratio (o/e) 0.83, 90% interval 0.65 to 1.06. The upper end of that interval is the gene's LOEUF score, 1.06, which puts it in group 4 of 6, group 1 being the genes least tolerant of losing a copy. Missense variants: 1,604 observed, 1,503.4 expected, observed/expected ratio (o/e) 1.07, 90% interval 1.02 to 1.11. Synonymous variants: 604 observed, 598.7 expected, observed/expected ratio (o/e) 1.01, 90% interval 0.94 to 1.08.
Homologues: Orthologues: chimpanzee STYXL2 (99% identical), macaque STYXL2 (96% identical), pig STYXL2 (87% identical), dog STYXL2 (82% identical), mouse Styxl2 (81% identical), rabbit STYXL2 (81% identical), rat Styxl2 (80% identical), guinea pig STYXL2 (78% identical), zebrafish dusp27 (39% identical). Paralogues in human: SSH2 (13% identical), SSH1 (11% identical), DUSP16 (10% identical), DUSP8 (9% identical), SSH3 (8% identical), DUSP1 (7% identical), DUSP7 (6% identical), DUSP29 (6% identical), DUSP5 (6% identical), DUSP4 (6% identical), DUSP13A (6% identical), DUSP6 (6% identical), and 19 more.
Diseases named in the same sentence as STYXL2 in open-access papers:
STYXL2 is named in the same sentence as 1 disease in open-access papers, as found by Europe PMC text mining. Sharing a sentence is not in itself a finding about the gene and the disease. The quoted sentences say what the papers report.
Paralysis (1 paper, 2021). Paralysis of voluntary muscles means loss of contraction due to interruption of one or more motor pathways from the brain to the muscle fibers. "The relationship of STYXL2 (DUSP-27) to diseases is not as well established as that of STYX and MK-STYX; however, STYXL2 may have a potential role in paralysis." (PMID 34203203, 2021).